GUSBP11 (GUSB pseudogene 11)
Gene: Transcribed unprocessed pseudogene on chromosome 22 (23,659,869 to 23,717,295, reverse strand). Ensembl gene ENSG00000272578.
Diseases named in the same sentence as GUSBP11 in open-access papers:
GUSBP11 is named in the same sentence as 15 diseases in open-access papers, as found by Europe PMC text mining. Sharing a sentence is not in itself a finding about the gene and the disease. The quoted sentences say what the papers report.
gastric cancer (4 papers, 2020 to 2023). A primary or metastatic malignant neoplasm involving the stomach. "GUSBP11 overexpression accelerated the viability and invasion of gastric cancer cells." (PMID 32411181, 2020). "GUSBP11, which was correlated with a poor prognosis in EOC, was upregulated in plasma from gastric cancer patients in comparison with healthy individuals." (PMID 37445988, 2023).
nasopharyngeal carcinoma (3 papers, 2022 to 2026). A carcinoma arising from the nasopharyngeal epithelium. "GUSBP11 has been found to regulate the progression of tumor, including triple negative breast cancer and nasopharyngeal carcinoma." (PMID 36685947, 2022).
triple-negative breast carcinoma (3 papers, 2022 to 2026). An invasive breast carcinoma which is negative for expression of estrogen receptor (ER), progesterone receptor (PR), and human epidermal growth factor receptor 2 (HER2). "GUSBP11 also enhances the expression of sphingolipid transporter 2 (SPNS2) in triple-negative breast cancer cell lines and suppresses the malignancy of triple-negative breast cancer cells by sponging miR-579-3p." (PMID 41431719, 2026). "Functional studies revealed that the binding of the YY1/p300/histone deacetylase 2 (HDAC2) complex to the GUSBP11 promoter is responsible for its reduced expression in triple-negative breast cancer cell lines." (PMID 41431719, 2026). "Additionally, they noticed that the overexpression of GUSBP11 repressed the epithelial-to-mesenchymal transition in the triple-negative breast cancer cell lines by increasing E-cadherin and decreasing the expression of matrix metallopeptidase 2 (MMP2), MMP7, N-cadherin, and vimentin proteins." (PMID 41431719, 2026).
head and neck squamous cell carcinoma (2 papers, 2020 to 2023). A squamous cell carcinoma that arises from any of the following anatomic sites: lip and oral cavity, nasal cavity, paranasal sinuses, pharynx, larynx, and salivary glands. "Conversely, GUSBP11 expression correlates with better prognosis in head and neck squamous cell carcinoma, bladder cancer, papillary renal cell carcinoma, and pancreatic adenocarcinoma." (PMID 37445988, 2023). "Moreover, differentially expressed GUSBP11 was identified in head and neck squamous cell carcinoma (HNSCC)." (PMID 32411181, 2020).
hepatocellular carcinoma (2 papers, 2023). A malignant tumor that arises from hepatocytes. "High expression of GUSBP11 in renal cancer is associated with a smaller tumor size and absence of metastasis, and SLC2A1-AS1 inhibits hepatocellular carcinoma progression and glycolysis through the STAT3/FOXM1/GLUT1 axis." (PMID 37020128, 2023). "In accordance with our data for EOC, high expression levels of GUSBP11 are predicted to bind miR-22-3p to avoid CCN2A mRNA degradation, correlating to poor overall survival in hepatocellular carcinoma patients." (PMID 37445988, 2023).
lung adenocarcinoma (2 papers, 2022 to 2025). A carcinoma that arises from the lung and is characterized by the presence of malignant glandular epithelial cells. "Studies found that GUSBP11 knockdown restrains the cell proliferation and metastasis of lung adenocarcinoma and promotes apoptosis." (PMID 40420632, 2025). "Recent studies have shown that downregulation of GUSBP11 inhibits growth and cell metastasis of lung adenocarcinoma and promotes cell apoptosis." (PMID 40420632, 2025).
glioma (1 paper, 2021). A benign or malignant brain and spinal cord tumor that arises from glial cells (astrocytes, oligodendrocytes, ependymal cells). "Among these, there were six lncRNAs (TTC28-AS1, AC090425.1, GUSBP11, LINC00092, HCG18, and FAM95B1) that have not been studied in gliomas, and we visualize the Kaplan–Meier analysis results (p < 0.05)." (PMID 34615480, 2021).
periodontitis (1 paper, 2020). An acute or chronic inflammatory process that affects the tissues that surround and support the teeth. "The PCR results, consistent with the microarray chip data, demonstrated that all the differentially expressed lncRNAs (FAM30A, GUSBP11, and LINC00525) were upregulated in periodontitis compared with those in controls." (PMID 32411181, 2020). "Besides, the level of lncRNAs (FAM30A, GUSBP11, and LINC00525) expression were positively correlated with the fraction of plasma cells in periodontitis." (PMID 32411181, 2020).
tumor (8 papers, 2022 to 2025). "Taken together, this study highlights that the inhibition of miR-605-3p by GUSBP11 to regulate the downstream signaling pathway leads to prognostic malignancy and promotes tumor growth in CRC." (PMID 40420632, 2025). "The data on the relationship between GUSBP11 and patients’ clinicopathologic characteristics showed that GUSBP11 correlated with tumor node metastasis (TNM) stage, distant metastasis, and recurrence (all P < .05)." (PMID 40420632, 2025). "According to the mean value of GUSBP11 in tumor tissues, all CRC patients were divided into a high GUSBP11 expression group (n = 158) and a low GUSBP11 expression group (n = 101)." (PMID 40420632, 2025). "Data validation in tissue samples confirmed that levels of CAMK2B and GUSBP11 were lower, while those of miR-432-5p were higher in tumor tissue than in paired tumor-adjacent tissue, suggesting a protective role of the axis in pRCC." (PMID 35626699, 2022). "Recent research has found that GUSBP11 was contained in a machine learning-based computational network for an indicator of immune infiltration of tumor microenvironment." (PMID 36685947, 2022). "Higher expression of GUSBP11 may promote the activation of the proliferation signal pathways in tumor cells, leading to an increase in the volume of the primary tumor focus and thus affecting the T stage." (PMID 40420632, 2025). "Upon further exploration, we found that high expression of lncRNA GUSBP11 is associated with no metastasis (P=0.0023), early-stage disease (P=0.0023), and small tumor size (P=0.0249)." (PMID 35127542, 2022). "Therefore, the influence of GUSBP11 on tumor characteristics was searched." (PMID 40420632, 2025). "Exploring the function of GUSBP11 in CRC progression and prognosis is important for tumor regulation." (PMID 40420632, 2025). "We detected lower levels of lncRNA GUSBP11 (P=0.0618) and CAMK2B (p=0.0447) in tumor tissue samples than in the normal tissue adjacent to the carcinoma, whereas levels of miR-432-5p were found to be higher in tumor tissue (P=0.0097)." (PMID 35127542, 2022). "The data of 215 samples in total were obtained from GEO database (98 normal tissues and 117 tumor tissues), and 1685 differentially expressed mRNAs (176 downregulated and 1509 upregulated) and 3 upregulated lncRNAs (MCM3AP-AS1, HCP5 and GUSBP11, all upregulated) were found." (PMID 35365175, 2022). "Glucuronidase, b pseudogene 11(GUSBP11), a long non-coding RNA, has been proved that might affect the development of tumor in recent research, but its molecular mechanism has not been explored clearly enough." (PMID 36742332, 2023).
cancer (4 papers, 2020 to 2025). A tumor composed of atypical neoplastic, often pleomorphic cells that invade other tissues. "Reports have demonstrated that lncRNAs are widely involved in the biological processes of cancer and that the lncRNA GUSBP11 has a potential impact on the development and prognosis of various cancers." (PMID 40420632, 2025). "The long non-coding RNA (lncRNA) GUSB Pseudogene 11 (GUSBP11) can act in a variety of cancers." (PMID 40420632, 2025). "GUSBP11 and LINC00525 were found to participate in the development of several cancers." (PMID 32411181, 2020).
GUSBP11 also shares sentences with these, for which no sentence is quoted: bladder cancer (1 paper); pancreatic adenocarcinoma (1); papillary carcinoma (1); papillary renal cell carcinoma (1); renal carcinoma (1).